IL6R (interleukin 6 receptor)
Diseases named in the same sentence as IL6R in open-access papers (continued):
Sharing a sentence is not in itself a finding about the gene and the disease.
tumor (continued). "We demonstrated that therapeutic blockade of IL-6R inhibits Bmi-1 function and suppresses Cisplatin-induced CSC self-renewal and tumor growth." (PMID 34689150, 2021). "Anti-IL-6R antibody therapy suppressed STAT3 activation and attenuated tumor burden in Apcmin/+Ripk3-/- mice." (PMID 33996591, 2021). "Conversely, the IL6R and IL6ST expression was regulated by a large number of miRNAs with a similar trend in different tumor types, indicating that miRNAs epigenetically regulate mainly the IL6 receptor complex." (PMID 34576335, 2021). "Tumor grade, serum CRP, and IL-6 levels in patients exhibiting a high expression of both IL-6 and IL-6R were high." (PMID 32138303, 2020). "Objective response rate (complete or partial response) was significantly correlated to tumor microenvironment-related SNPs concerning CCL2, NOS3, IL1RN, IL12B, CXCR3, and IL6R genes." (PMID 32733486, 2020). "In C26 tumor-bearing BALB/c mice, involvement of myokines was further indicated as increased muscle IL-6, IL-6R, and myostatin expression accompanied muscle wasting in these mice." (PMID 33329046, 2020). "IL6R, PLCG1, PTPN1, and HCK are involved in cytokine/interferon signaling to activate immune cells to counter proliferating tumor cells." (PMID 30978274, 2019). "In prostate cancer bone metastases, which are largely poorly immunogenic, high tumor cell STAT3 phosphorylation, and IL-6R have been observed, as compared to lymph node and visceral metastases." (PMID 31842362, 2019). "CAFs secrete IL-6 in the tumor microenvironment, which contributes to an up-regulation of HK2 via the IL-6R." (PMID 31212816, 2019). "The expression levels of IL6R in the epithelial and stromal compartments in the SCC tumours was significantly higher compared with the OAC tumours (for the core and leading edge tissue, all p values < 0.001)." (PMID 29890775, 2018). "Inhibition of IL-6R signalling or IL-6R siRNA increased MAO-A activity and inhibited tumour angiogenesis and invasion significantly in different models." (PMID 29695771, 2018). "Consistently, double knockout mice show a further reduction in tumor burden in DEN-induced HCC when compared to control and single LepRL−KO/IL-6Rα knock out mice, whereas metabolism remained largely unaltered between the genotypes." (PMID 30224299, 2018). "The IL-6R intensity levels were higher in the SCC tumours compared with the OAC tumours for the core and leading edge tumour tissue." (PMID 29890775, 2018). "The robust suppression of T cells was recovered when IL-6R Ab or JSI-124 was administrated, which implied that tumor-derived IL-6 was the key trigger that regulated the development of competent e-MDSCs." (PMID 30083161, 2018). "Functional effects of genetic knockdown and overexpression of IL6R or IL6 stimulation were examined in vitro and in tumours in vivo." (PMID 29258522, 2017). "Overall, our findings of the anti-proliferative effects of miR-218 in lung adenocarcinima cells, through the direct targeting of IL-6R and JAK3, further corroborate a tumor suppressive role for miR-218 in NSCLC." (PMID 28830450, 2017). "Through binding with IL-6R, IL-6 activates JAK-STAT3 signaling pathway and in turn confers tumor cells proliferation advantages." (PMID 28036277, 2017). "The trimeric interaction of IL-6 with soluble IL-6R and the common gp130 subunit is known to activate STAT3 and promote tumor growth." (PMID 29207662, 2017). "IL10 and the gene encoding its receptor IL10R were expressed mainly by TAMs, LIF and LIFR by tumor cells, IL6 and the genes for IL6 receptor subunits IL6R and IL6ST by both cell types." (PMID 27215396, 2016). "RT-PCR analysis of primary ES tumors confirmed the expression pattern of cell lines with strong expression of IL6R and IL6ST in all tumor samples." (PMID 26215971, 2015). "Peritumoral IL-6, IL-6R, gp130, CD68, and HIF-1α expression, as well as MVD, gradually increased during tumor growth." (PMID 26525581, 2015).
tumor (continued). "We observed a parallel increase in STAT3 and IL-6R in HCV-infected HCC as compared with control liver, suggesting coordinate regulation of inflammatory response molecules in tumor development." (PMID 26217396, 2015). "Evaluating with Oncomine data, we found most target genes (BCL2, ERBB2/3, SIRT7, ETS1, Mcl-1, IL6R, and LIN28B) were significantly activated in HCC tumor tissues, consistent with miR-125b underexpression." (PMID 25861255, 2015). "Expression levels of multiple genes encoding for cytokines or cytokine receptors over-expressed in tumor cells or ascites fluid, such as CXCL1, CXCL2, CXCL3, IL8, IL6, IL6R, and CXCR4 were reduced in OV3/COX1KD cells." (PMID 25972361, 2015). "Gelatinase activity was one major GO annotation of these eight genes (CA7, SPIB, GUCA2B, AQP8, IL6R, SPP1, TCN1, and CWH4) and is related to tumor progress and metastasis." (PMID 24959000, 2014). "Taken together, these data suggest that activation of the IL-6R, Syk, and JNK pathways are required for IL-6-induced AP-1 activation and tumor metastasis in human OSCC cells." (PMID 24398980, 2014). "IL-6 increases ICAM-1 expression through the IL-6R, Syk, JNK, and AP-1 signaling pathways and induces tumor migration." (PMID 24398980, 2014). "From these experiments, we provide novel information regarding potential tumor-MDSC synergistic axis involving IL-6 and soluble IL-6Rα." (PMID 24021059, 2013). "IGROV1-Luc tumour cells in vitro secreted TNF-α, TNFR1-α, TGF-α, AREG, HB-EGF and IL-6Rα, all known substrates for the shedding activity of ADAM17, into the culture medium even when unstimulated." (PMID 22792380, 2012). "The potential importance of other immune system-related ADAM17 substrates as IL-6R or MIC-A/B, the ligands of NKG2D receptors, in murine tumor development is questionable because of species specificity." (PMID 23251384, 2012). "Our results stress the importance to evaluate the endogenous levels of IL-6 and IL-6Rα in each NPC individually, if cultured NPC cells of the given tumor are to be considered for making tumor vaccines." (PMID 19497133, 2009). "This study investigates both the expression levels and activation of the IL-6R/JAK/STAT3 pathway in matched hormone-sensitive and hormone-refractory tumours from the same patient." (PMID 17595657, 2007). "Immunohistochemistry using IL-6R, JAK1, STAT3, pSTAT3Tyr705 and pSTAT3Ser727 antibodies was performed on 50 matched hormone-sensitive and hormone-refractory tumours pairs." (PMID 17595657, 2007). "Through integrated single-cell multi-omics analysis of paired peripheral blood, synovial fluid, and tumor samples from longitudinal ICI-IA cohorts and matched controls, we identified a unique regulatory T-cell (Treg) population co-expressing CD137 and IL-6R (AtpTreg)." (PMID 42118587, 2026). "Interestingly, we found that IL-6R blockade drastically increased the frequency of CD8+ macrophages in tumors, which was negatively correlated with tumor T-cell infiltration." (PMID 39653766, 2025). "Preclinical studies have also shown that IL-6R blockade or genetic ablation of CD8+ T cell intrinsic IL-6 signaling synergized with anti-PD-L1 therapy to enhance antitumor responses, leading to improved tumor control." (PMID 40255422, 2025). "Future studies should incorporate immunohistochemical analyses of tumor-infiltrating immune cells (e.g., CD4+ and CD8+ T cells, IL-6R expression, macrophage markers) to delineate the relationship between systemic cytokine alterations and intratumoral immune activity." (PMID 41303495, 2025). "This could be attributed to IL-6 use by FRCs and LECs, which also express IL-6R, although to a lower extent than the DLBCL tumor cells." (PMID 40061210, 2025). "In addition, tumor-produced IL-6 has been shown to reduce the expression of MHC-II in myeloid cells in the TME, which can be recovered by IL-6R blockade." (PMID 39653766, 2025).
tumor (continued). "Transwell coculture results revealed that MDSCs cocultured with tumor cells with decreased USP25 expression displayed increased chemotactic activity in vitro, and this effect was abrogated upon treatment with an anti-IL-6 receptor antibody (IL-6R Ab)." (PMID 41326342, 2025). "IL-6/IL-6R/GP130 signaling is responsible for innate and acquired immune responses but is frequently hijacked in multiple cancer types to promote anti-immune evasion and a pro-inflammatory tumor microenvironment." (PMID 39768178, 2024). "Interestingly, the results showed that the IL-6 receptors IL6R and GP130 were highly expressed not only in tumor cells but also in TAMs." (PMID 38424624, 2024). "Notably, researches have demonstrated that activation of IL-6/IL-6R up-regulates VEGF, thereby promoting tumor angiogenesis 33,34." (PMID 39247606, 2024). "Moreover, the AKR1C1+ inflammatory fibroblast strongly expresses IL6 which interacts with IL6R expressed on DC1 and PRR-induced mo-DC, potentially contributing to tumor growth and therapeutic resistance." (PMID 38744958, 2024). "Similarly, studies show that IL6-induced chemoresistance is developed by cross-talk of MAPK/ERK and NFκB signaling; thus, upstream blockage of these pathways can potentiate the anti-tumor response of anti-IL6 and anti-IL6R antibodies." (PMID 39766086, 2024). "In SA region, the expression of IL-6, gp130, and JAK2 was lower in tumor tissues in IL-6+gp130+, IL-6+JAK2+, and IL-6+gp130+JAK2+ cells (P < 0.05); and the expression of IL-6R, CRP was also lower in tumor tissues in IL-6R+CRP+, IL-6R+STAT3+, and IL-6R+CRP+STAT3+cells (P < 0.05)." (PMID 38881895, 2024). "Indeed, research derived from the Cancer Genome Atlas (TCGA) database proved that the IL-6R/STAT3/miR-34a loop is active in primary human CRCs, contributing to a mesenchymal phenotype of tumor cells, along with invasion and metastasis." (PMID 38256960, 2024). "During the late stages of CAC development, tumor-derived sIL-6R rather than membrane-bound IL-6R induces STAT3 activation and accelerates tumor growth." (PMID 38182653, 2024). "C/EBPδ inhibits FBXW7 in ER + cells, releasing HIF-1α and IL-6Rα expression and activating downstream STAT3 phosphorylation, promoting in vitro calmodulin transformation, sphere formation, and patient-derived xenograft (PDX) tumor metastasis." (PMID 37658431, 2023). "In addition, IL-6 was detected in MDCS, and the IL-6R-neutralizing antibody inhibited both STAT3 activation and tumor proliferation induced by MDCS stimulation in both tumor cell lines." (PMID 36961655, 2023). "Addition of IL-6Rα antagonist to cultures reversed tumor EMT but did not alter PIT activation, cytokine secretion or cytotoxicity." (PMID 37063842, 2023). "We speculate that sustained IL-6/IL-6Rα signaling during EMT-MET plasticity states further drives the modification of MPE environment, amplifying the aggressive MPE tumor state." (PMID 37063842, 2023). "Combined with ovalbumin immunization, PD-L1 blockade increased the polyfunctional anti-tumor CTL response in mice that received Il6r−/− OT-I cells, but not Il6rwt/wt cells." (PMID 36599350, 2023). "In fact, higher STAT3/pSTAT3 and IL-6R expression was found in CAFs compared to tumor cells (data not shown)." (PMID 36639824, 2023). "Disruption of the IL-6/IL-6R/STAT-3 axis using Stt and Tcz may be a therapeutic target in PCa based on the molecular characteristics of the tumor cells." (PMID 35703345, 2022). "Targeting IL-6R and IL-11R in mouse models can significantly reduce STAT3 activation and enhance the effect of chemotherapy agents such as gemcitabine in tumor killing effect, suggesting that the interleukin pathway may be a good therapeutic target." (PMID 35965504, 2022). "Previous study demonstrated that DLBCL has pro-tumor mechanisms by expressing IL-6/IL-6R and inhibiting negative regulator, eventually promoting the constitutive activation of IL-6/IL-6R axis." (PMID 36104733, 2022).
tumor (continued). "We also provide evidence that the RV-promoted switch toward quiescence was sustained by negative feedback on the IL-6R/STAT3 pathway, which has been associated with tumor growth, angiogenesis, chemoresistance, and immune suppression." (PMID 35565270, 2022). "Diacerin treatment reduces protein expression of IL-6Rα, pSTAT3, pMAPK, pAKT in TNBC tumor sections indicating diacerin could inhibit multiple IL-6-regulated oncogenic pathways." (PMID 35371975, 2022). "The trans pathway is critical in the context of cancer because it influences tumour and surrounding stromal cells that do not express IL-6R, thus modifying the activity and recruitment of cells into the TME." (PMID 36429126, 2022). "In contrast, Il6r mRNA was significantly increased in the quadriceps (8.9-fold, P = 0.0001) and liver (2.6-fold, P = 0.002) but was unchanged in the adipose tissue from KPC tumor mice." (PMID 33851955, 2021). "IL-6 binds with IL-6R to induce the activation of STAT3, and activated STAT3 binds to the promoter region of the VEGF gene to increase transcription, promoting the formation of tumor angiogenesis." (PMID 34976809, 2021). "Binding of IL-6 to its receptor IL-6R in cancer cells activates multiple cellular signalling pathways including JAK/STAT, PI3K/Akt, leading to enhanced expression of a variety of promoters of tumour growth, angiogenesis and cancer progression." (PMID 34223877, 2021). "Since the onset of inflammation and carcinogenesis can be regulated by epigenetic events, we aimed to investigate the interplay among DNA methylation, miRNA expression, and gene expression of IL6, IL6R, including transmembrane isoform, and IL6ST in different tumor types." (PMID 34576335, 2021). "An interesting point is that even if tumor cells do not express IL-6 receptor (IL-6R), the soluble form of IL-6R can activate IL-6." (PMID 32674405, 2020). "We observed a non-significant difference in IL6 gene expression between tumor and non-tumor in AA and a 5.2-fold increase of the cytokine in tumors from CA as well as a non-significant reduction (−3.18 fold) of the IL6R gene only in CA." (PMID 32983990, 2020). "We also tried to quantify the IL-6 and IL-6R levels using real- time PCR, but the tumor sample was not large enough to evaluate them." (PMID 32138303, 2020). "Furthermore, gp130, IL6Rα, and IL31 were suggested to predict prognosis among tumor HPV-negative patients." (PMID 33066437, 2020). "Finally, for further confirmation, a paraffin-embedded portion of each tumor was cut at 5 μm and IHC stained using anti-CK5 (basal marker), anti-CD90 (infiltrated mouse MSC-specific marker), and anti-IL-6R antibodies." (PMID 31014367, 2019). "Strikingly, the D-KO mice displayed a full protection against the development of large tumors and a reduced total tumor burden compared to IL-6Rα single knockouts, which grants LEPR signaling a compensating tumor-promoting effect in DEN induced HCC development." (PMID 30224299, 2018). "IL6R is bound by its IL-6 ligand and can activate downstream signaling pathways, such as MAPK, PI3K, and signal transducer and activator of transcription 3 (STAT3), which promotes tumor cell proliferation." (PMID 29626935, 2018). "Additionally, we undertook a study to examine the two key signaling components, namely, IL-6R and pSTAT3 in SCC and OAC tumours, respectively." (PMID 29890775, 2018). "Above data implied that tumor-derived IL-6 predominantly triggered SOCS3 suppression in e-MDSCs, and hence it could be reversed by using the IL-6R blocking antibody." (PMID 30083161, 2018).
tumor (continued). "Moreover, miR-204 effectively suppressed the development of tumor growth in an animal model of EOC, which was impaired by IL-6R re-expression." (PMID 28388577, 2017). "Like TNF-α, IL-6 facilitates tumor development by promoting the conversion of non-cancer cells into tumor stem cells in vitro via Oct4 gene upregulation expression through IL-6R/JAK/STAT3 signaling." (PMID 28030810, 2017). "The respective median survival was augmented by at least 18 months in comparison to patients with tumor specimens showing either only IL-6Rα or nuclear STAT3 or neither of the two." (PMID 27191495, 2016). "In this study using bioinformatic technology, we found that IL-6R, SOS-1, NF-IL-6, c-Fos, MAP3K10, NIK, SP1, MEF2, and other inflammatory factors and tumor regulatory molecules are also potential target genes of miRNA-155, but no definitive results have been reported yet." (PMID 27462776, 2016). "Like TNF-α, IL-6 facilitates tumor development by promoting the conversion of non-cancer cells into tumor stem cells in low-attachment culture conditions by up-regulating Oct 4 gene expression through activating the IL-6R/JAK/STAT3 signaling pathway." (PMID 26418748, 2015). "By IHC analysis of TMA slides, IL-6 receptor (IL-6R) was expressed in both tumor tissues and adjacent non-malignant epithelial tissues." (PMID 23561329, 2013). "One experimental study has shown that human lung CSC-derived tumor contained 2–3 higher levels of inflammatory cytokines including IL-6, which is consistent with recent findings showing that the lung CSC-like cells have high level expression of IL-6/IL-6R." (PMID 22952749, 2012). "A study reported the combined use of tocilizumab (anti-IL-6R) and bevacizumab (anti-VEGF) in two patients with recurrent cystic ACPs, resulting in significant responses, including reduced cystic tumor burden and tumor stability, suggesting a viable therapeutic alternative." (PMID 40433410, 2025). "STAT3 activation and subsequent tumor development do not occur without the Glycoprotein 130 (gp130) receptor, which is a signaling element of the IL-6R‒gp130 complex, and the IL-6 family member IL-11 is a promotion element of GC by activating STAT3 to overexpress proliferative genes in mice." (PMID 40264171, 2025). "Selective inhibition of the trans‐signaling pathway may be beneficial for tumor patients with limited or no IL‐6R expression." (PMID 40166646, 2025). "In TME, IL‐6 and CCL2 trigger autophagy, respectively, by binding to interleukin 6 receptor (IL‐6R) and CC chemokine receptor 2 (CCR2) and induce macrophage towards M2 type, which is strong support for maintaining inhibitory TIME and promoting tumour progression." (PMID 38652105, 2024). "Inhibition of IL-6R, PD-L1 or EGFR resulted in CXCL7 decline, and shCXCL7 decreased MCT-1, IL-6/IL-6R, p-EGFR and PD-L1, which may potentiate therapeutic efficacy against tumor spreading via lymphatic circulation." (PMID 38505617, 2024). "On day 10 post tumor challenge, when levels of the three pro-inflammatory cytokines were still low, we began injections of validated blocking antibodies targeting TNFα, IL-1β, IL-6R, or no blockade." (PMID 37461742, 2023). "Although IL-6R and IL-11R are expressed in specific cell types, gp130 is ubiquitously expressed allowing for the activation of intracellular STAT3 signaling in cells with limited or no IL-6R and IL-11R expression, via sIL-6R and sIL-11R by tumor infiltrating neutrophils, monocytes and T-cells." (PMID 35053592, 2022). "Finally, tocilizumab will neutralize IL-6 signaling by antagonizing IL-6R regardless of the cellular source of IL-6 in the tumor microenvironment." (PMID 35260569, 2022). "On the other hand, anti‐mouse IL‐6R antibody given by i.p. injection twice a week from day 7 to day 21 after inoculation, did not inhibit tumor growth in the N‐inv model (rat IgG [control] vs. anti‐mouse IL‐6 antibody [mean ± SD], 0.865 ± 0.623 g vs. 1.561 ± 0.755 g; p = 0.173)." (PMID 35578571, 2022).